RN7SKP172 (RN7SK pseudogene 172)
Gene: Miscellaneous RNA gene on chromosome 12 (76,315,751 to 76,316,048, forward strand). Ensembl gene ENSG00000223273.
Homologues: Orthologues: chimpanzee 7SK (99% identical). Paralogues in human: RN7SKP255 (75% identical), RN7SKP176 (74% identical), RN7SKP79 (74% identical), 7SK (73% identical), RN7SKP90 (73% identical), RN7SKP180 (72% identical), RN7SKP189 (72% identical), RN7SKP203 (72% identical), RN7SKP202 (71% identical), RN7SKP118 (71% identical), RN7SKP131 (71% identical), RN7SKP221 (71% identical), and 284 more.